BRCA1 (BRCA1 DNA repair associated)
Diseases named in the same sentence as BRCA1 in open-access papers (continued):
Sharing a sentence is not in itself a finding about the gene and the disease.
breast cancer (continued). "Thereby, we speculate that the lack-of-HP1-expression in some breast cancer tumors can deregulate their BRCA1 functions in homologous recombination repair and cell cycle checkpoint control." (PMID 25769025, 2015). "BRCA1-IRIS expression is elevated in the majority of breast cancers, including TNBCs." (PMID 25583261, 2015). "Over 60% were diagnosed at Stage I (30.2%) or II (31.7%); 64.8% did not know their breast cancer subtype; and 64.4% did not know their breast cancer susceptibility gene mutation (BRCA1 or BRCA2) carrier status." (PMID 25853030, 2015). "In survival studies looking at the prognostic effect of BRCA1/2 mutation in breast cancer, no OS differences have been demonstrated." (PMID 25605252, 2015). "DNA promoter hypermethylation may be the potential mechanism accounting for BRCA1 expression silence in part of sporadic types of breast cancer." (PMID 25789047, 2015). "Since BRCA1 associated breast cancers are frequently classified as hormone receptor negative or even triple negative, the application of endocrine therapies is rather limited in these patients." (PMID 26029931, 2015). "Since EPA and perhaps its metabolites are also PPARγ agonists the increased expression of BRCA1 mRNAa in the breast cancer xenografts of mice fed the fish-oil supplemented diet could be explained, at least in part, by increased transcription." (PMID 25762631, 2015). "In contrast to currently held beliefs of some oncologists, current evidence does not support worse breast cancer survival of BRCA1/2 mutation carriers in the adjuvant setting; differences if any are likely to be small." (PMID 25816289, 2015). "Yet, the role of BRCA1 as a driving gene in sporadic breast cancer is, at best, far from clear." (PMID 25884417, 2015). "Immunohistochemistry was used to examine the expression of PARP1 and BRCA1/BRCA2 in breast cancer." (PMID 25865228, 2015). "Five hundred μg of proteins extract from MCF-7 and HCC1937 breast cancer cell lines were subjected to immunoprecipitation with a monoclonal antibody directed against the C terminus of BRCA1 (D9-Santa-Cruz), followed by immunoblotting with an anti-ATF1 antibody." (PMID 26061043, 2015). "In the present study we employed whole-exome sequencing of seven cases diagnosed with familial breast cancer and with unknown BRCA1 or BRCA2 status." (PMID 25923920, 2015). "Our own experience compared 105 female BRCA1/2 mutation carriers with unilateral breast cancer to matched mutation carriers who did not undergo CRRM." (PMID 25692038, 2015). "The presence and distribution of multiple uORFs in the 5′UTR of BRCA1 mRNAb suggested to us that this alternative transcript, usually found in breast cancer cells, could be translationally up-regulated by agents that induce phosphorylation of eIF2α." (PMID 25762631, 2015). "We performed a genome-wide association study comparing 1431 Sardinian patients with non-familial, BRCA1/2-mutation-negative breast cancer to 2171 healthy Sardinian blood donors." (PMID 25956309, 2015). "Since BRCA1 is also involved in DNA repair and genomic stability, it has been proposed that BRCA mutations or functional abnormalities would result in accumulation of genetically unstable mammary stem cells and thus a step towards breast cancer." (PMID 26504831, 2015). "Interestingly, by comparing SUM149PT and MCF-7 transfected breast cancer cells, a reduction of pro-angiogenic VEGFA and ANGPT2 mRNA level was observed only in BRCA1 deficient cells transfected by hsa-miR-573 mimic." (PMID 25333258, 2015). "It is conceivable that in the progressive transformation from normal to malignant cells in sporadic breast cancers, the relative abundance of the inefficiently translated BRCA1 mRNAb transcript may play an role in the reduced expression of BRCA1 protein." (PMID 25762631, 2015).
breast cancer (continued). "Contrary to non-hereditary breast cancers, tumors arising in women carrying a germline BRCA1 mutation present preferentially with a basal-like subtype and thus in most cases a triple negative phenotype in ∼85% of the cases." (PMID 26426992, 2015). "Interestingly, Sox11 is a transcriptional regulator upregulated in BRCA1-mutant breast cancers and has been shown to promote cell survival and proliferation in breast cancer cells." (PMID 26429062, 2015). "Interestingly, increased levels of claudin 1 have also been reported for medullary and BRCA1-type breast cancers as well, and it was further proposed that claudin 1 expression can be used to discriminate mutation carriers from sporadic breast cancer cases." (PMID 26633531, 2015). "The overall frequency of the RECQL germline mutations in the 448 familial breast cancer patients without BRCA1/2mutations was 2.0% (9 of 448)." (PMID 25945795, 2015). "Transcriptional suppression of the IGF-1R gene by BRCA1 has also been reported in breast and endometrial cancer, and loss-of-function mutation of BRCA1 leads to amplification and constitutive activation of the IGF-1R pathway in breast cancer." (PMID 26510816, 2015). "The ‘normal’ samples were tumour-associated normal breast tissue removed at the time of definite surgery in the Caucasian patients diagnosed with breast cancer lacking any known germ-line mutations in BRCA1 or BRCA2." (PMID 26300993, 2015). "Our review shows that, in contrast to currently held beliefs of many oncologists and despite 66 published studies, it is not yet possible to draw evidence-based conclusions about the association between BRCA1 and/or BRCA2 mutation carriership and breast cancer prognosis." (PMID 25816289, 2015). "Our aim is to characterize in detail mitochondrial genome variability of women with a strong familial history of breast cancer, but without BRCA1/2 pathogenic mutations." (PMID 26406445, 2015). "For these reasons, we have sequenced the mitochondrial genome of 436 women diagnosed with breast cancer, having a positive familial breast cancer history, but testing negative for BRCA1/2 pathogenic mutations." (PMID 26406445, 2015). "It has been reported that their phenotypic and molecular similarity to BRCA1-related breast cancers might provide implications in terms of treatment." (PMID 26196284, 2015). "The data indicated that the expression of BRCA1 in breast cancer was aberrantly reduced." (PMID 25789047, 2015). "Thus, although our results consistently show a lack of relationship between decreased BRCA1 expression and basal-like breast cancer, they cannot definitively exclude a role for BRCA1 dysfunction in sporadic basal-like breast cancer." (PMID 25825707, 2015). "The current study is the first study performing mutation analyses in BRCA1, BRCA2 and PALB2 and determining the frequency of CHEK2 c.1100delC in triple negative and/or premenopausal breast cancer patients in South Africa through both next generation sequencing and large rearrangement testing." (PMID 26577449, 2015). "Resveratrol, a phytoalexin produced by plants such as the Japanese knotweed, prevents hypermethylation of the BRCA1 promoter, and may be effective for triple negative or basal subtype breast cancers." (PMID 25869442, 2015). "Our data show that, in the time period 2001–2009, BRCA1/2 mutation carriers who were not aware of their carrier status at the time of their breast cancer diagnosis, had diagnostic DNA testing sooner after diagnosis than those in the time period 1995–2000." (PMID 25700605, 2015). "Genetic testing at the time of diagnosis facilitates choice of treatment and BRCA1 carriers with breast cancer may benefit from bilateral mastectomy, from oophorectomy and from cisplatinum treatments." (PMID 26468334, 2015). "Notably, promoter methylation of BRCA1 was also found in 46 % of pancreatic neoplasms suggesting a broader impact of this alteration, beyond ovarian and breast cancers." (PMID 25986046, 2015).
breast cancer (continued). "Previously, AZD2281 was evaluated in a genetically engineered mouse model of BRCA1 breast cancer." (PMID 25975349, 2015). "With regard to the results obtained for BRCA2 mutation carriers, the opposite direction of the potential association with ERα-negative breast cancer compared with the association observed for BRCA1 mutation carriers is intriguing." (PMID 25830658, 2015). "In this study we have performed a deep characterization of mitochondrial genome variability among 436 women diagnosed with breast cancer, having a positive familial breast cancer history, and negative for BRCA1/2 mutation screening." (PMID 26406445, 2015). "BRCA1 methylation in blood from breast cancer patients could provide a potential mechanism for cancer susceptibility in the Saudi population and offer a promising tool for the detection of cancer predisposition." (PMID 25951871, 2015). "Methylation of the BRCA1 promoter along with the corresponding loss of BRCA1 expression in mutation-negative breast cancer is well described for both familial and sporadic breast cancer and has been demonstrated using low-throughput loci-specific methods." (PMID 26438025, 2015). "For these reasons, we propose an exploration of the variability of the mitochondrial genome in individuals diagnosed with breast cancer, having a positive breast cancer family history but testing negative for BRCA1/2 pathogenic mutations." (PMID 26406445, 2015). "UBE2T has been also found overexpressed in lung, bladder and prostate cancers and may act as oncogene-like gene in breast cancer by repressing BRCA1 expression and promoting the proliferation and transformation of breast cancer cells." (PMID 26308072, 2015). "It validates the concept that porcine transgenic animal models may be valuable for the study of human breast cancer and the development of novel therapeutics for the treatment of breast cancer driven by BRCA1 defects." (PMID 26379698, 2015). "Although germline mutations of high-penetrance genes such as BRCA1/2 are implicated in development of hereditary breast cancers, at least half of all breast cancer families are not linked to these genes." (PMID 25927356, 2015). "It has been proved that BRCA1 mutation is one of the main genetic events in the hereditary type of breast cancer, but no or limited somatic mutations in BRCA1 have been found in the sporadic form of breast cancer." (PMID 25789047, 2015). "Clinical presentation of the tumor, HER2-positivity, genomic profile and loss of the mutated BRCA1 allele in tumor evidence that BRCA1 is not inactivated in this breast cancer." (PMID 26426992, 2015). "Our aim was to investigate miRNA-mediated regulation of angiogenesis in a series of familial breast cancers stratified by BRCA1/2 mutational status in BRCA carriers and BRCA non-carriers (BRCAX)." (PMID 25333258, 2015). "PBSO before the age of 50 years decreases breast cancer risk in BRCA1/2 mutation carriers without prior breast cancer (HR 0.36–0.63)." (PMID 26000714, 2015). "Furthermore, in the latest large multiple center study, 1,583 patients with BRCA1 mutations and 881 with BRCA2 mutations, 383 (24%) and 454 (52%) of patients were administered tamoxifen, respectively, following the initial breast cancer diagnosis." (PMID 25435968, 2015). "For the participants who were BRCA1/2 mutation carriers with a family history of breast cancer, the risk of OC was not known until it was disclosed during the genetic testing and counselling process." (PMID 25391615, 2015). "Finally, we assessed the potential correlation between RAD17 and BRCA1 DNA repair genes expression and clinical outcome in a cohort of sporadic basal-like breast carcinomas (BLCs)." (PMID 25650659, 2015). "It is still unclear whether the overexpression of P-cadherin in the BRCA-1 inactivated basal-like breast carcinomas is related to the transformation of the luminal progenitor, which is the cell-of-origin that has been described for this malignancy." (PMID 26438065, 2015).
breast cancer (continued). "Piccirilli and co-authors have also studied 11 cases of GBM occurring after mammary carcinoma, but their genomic status concerning BRCA1 was unknown." (PMID 25880076, 2015). "Whilst BRCA1 and BRCA2 are considered “high risk” the other five members of this network component are considered “moderate risk” with a two- to fourfold increased breast cancer risk relative to the general population (10%)." (PMID 24550935, 2014). "Our finding indicates involvement of hereditary factors in non-BRCA1/2 breast cancer families in which family members may carry genetic susceptibility not just to breast cancer but to a particular subtype of breast cancer." (PMID 24479546, 2014). "Also, BRCA1 and BRCA2 genetic testing was performed to determine the association between gene mutations and the development of other tumors, including breast cancer." (PMID 24959251, 2014). "However, it was shown that several cell lines derived from mouse BRCA1 mutant mammary cancers and a human pancreatic BRCA2 mutant cancer cell line exhibited resistance to PARPi." (PMID 24962108, 2014). "Clinical and pathological features of BRCA1 c.190T>C related breast cancer cases." (PMID 24516540, 2014). "Interestingly, the BRCA1 signature also significantly predicted the future development of invasive non-breast cancers (AUC = 0.62; 0.50 to 0.74; P = 0.04)." (PMID 25067956, 2014). "Women with mutations in BRCA1 or BRCA2 gene are 3 to 7 times more likely to develop breast cancer than the women without mutations in those genes, with excessive relative risks of about 30-fold for early onset diseases (before the age of 45)." (PMID 24711893, 2014). "Based on these findings, we hypothesized that regulation of ID4 mediated by miR-342 could be involved in the pathogenesis of breast cancer by downregulating BRCA1 expression." (PMID 24475217, 2014). "A BD-L signature is enriched in HER2+ breast cancer brain metastases without pathogenic BRCA1 mutations." (PMID 24625110, 2014). "Although several studies have indicated the association between the presence of methylated BRCA1 promoter in WBC and the risk of developing breast cancer, the pathological significance of methylated BRCA1 promoter in WBC of cancer-free women remains still unclear." (PMID 25403427, 2014). "While most cases of breast cancers occur in women without a family history, about 10% of cases are found in women with mutations in BRCA1 or BRCA2 genes." (PMID 24523856, 2014). "Therefore, it is of interest to consider this metal-based compound as a therapeutic agent perhaps for aggressive triple-negative and BRCA1-defective breast cancers (TNBC)." (PMID 24507701, 2014). "Our findings imply that genetic (such as BRCA1 mutation) and epigenetic mechanisms (such as DNA methylation, histone modification, transcription factor binding) are jointly involved in the malignant progression of DNMT1-related breast cancer." (PMID 24502362, 2014). "Perifosine prevents proliferation of breast cancer cell lines in a BRCA1-dependent manner." (PMID 25426449, 2014). "This implied that the increase in the ruthenium sensitivity in BRCA1 defective breast cancer cells might be related to a dysfunctional BRCA1 that is unable to repair DNA damage produced by ruthenium treatment, and ultimately led to breast cancer cell death." (PMID 24507701, 2014). "The entire pathway was thus modified in breast cancer cells expressing BRCA1 wild-type protein." (PMID 25010005, 2014). "There was no significant alteration in the S phase observed for the BRCA1-associated breast cancer cells." (PMID 24507701, 2014). "Despite this, the majority of women with a family history of breast cancer who undergo genetic testing do not carry a BRCA1/2 mutation." (PMID 24667084, 2014).
breast cancer (continued). "BRCA1 mutation non-carriers were more likely to succumb to breast cancer than BRCA1 mutation carriers [18 (23.1%) vs. 2 (5.3%), respectively; P<0.014]." (PMID 24348864, 2014). "Post-translational modification of BRCA1 proteins could prevent the binding of BRCA1 to UBC9 resulting in breast cancers." (PMID 23873416, 2014). "Several PI3K inhibitors favorably reduce proliferation of BRCA1-defective breast cancer cells." (PMID 25426449, 2014). "Absence of overlapping mutations between the BRCA1+ genomes and sporadic breast cancer genomes suggests the different genetic basis between these two types of breast cancer." (PMID 24884718, 2014). "We identified 22 (14.2%) breast cancer patients harboring methylated BRCA1 promoter." (PMID 25403427, 2014). "These are the most strongly associated loci for overall breast cancer in BRCA1 carriers, but they had not previously been investigated for their roles in subtypes other than ER." (PMID 25919761, 2014). "These predictors would be useful in genetic counseling and decision-making for a genetic test but they are still of limited value since a considerable number of BRCA1 or BRCA2 mutations are observed in breast cancer families without such risk factors." (PMID 24591761, 2014). "Large genomic rearrangements (LGRs) in the BRCA1/2 genes are frequently observed in breast cancer patients who are negative for BRCA1/2 small mutations." (PMID 25176351, 2014). "Indeed, depletion and functional impairment of DDR and HR proteins, including BRCA1, is well documented to induce genome instability and defective DNA repair, as well as to sensitize breast cancer cells to DNA damaging agents." (PMID 25026298, 2014). "The screening of BRCA1 and BRCA2 mutations is now an established component of risk evaluation and management of familial breast cancer, early-onset breast cancer and bilateral breast cancer patients." (PMID 24961674, 2014). "Hypermethylation of the DNA repair gene BRCA1 in sporadic triple-negative breast tumors has also been proposed as a biomarker to predict sensitivity of breast cancers to the cross-linking agent cisplatin and to the poly(ADP)-ribose polymerase inhibitor olaparib." (PMID 25473433, 2014). "However, it has also been reported that AKT phosphorylation has an inverse correlation with BRCA1 expression in human breast cancers." (PMID 25426449, 2014). "We conducted analyses of large pathology datasets accrued by the Consortium of Investigators of Modifiers of BRCA1/2 (CIMBA) and the Breast Cancer Association Consortium (BCAC) to reassess previously reported histopathological predictors of BRCA1 and BRCA2 mutation status." (PMID 25857409, 2014). "However, future trials need to be considered before utilizing BRCA1 as a promising therapeutic target for breast cancer treatment." (PMID 24507701, 2014). "While there are evidence-based practices for managing women with a BRCA1/2 mutation, there is little evidence to guide practitioners on how women from families with breast cancer history and without BRCA1/2 mutations should be managed." (PMID 24667084, 2014). "BRCA1 and BRCA2 are the two major breast cancer susceptibility genes." (PMID 24728327, 2014). "In addition, the ER-specific associations in BRCA1 and BRCA2 carriers were mainly in the same direction and of a magnitude similar to the associations observed with breast cancer stratified by ER expression status in the general population." (PMID 25919761, 2014). "Similarly, we have recently reported BRCA1 promoter hypermethylation in WBC genomic DNA of 2 out of 7 (28.5%) breast cancer patients, whose tumors showed BRCA1-like characteristics." (PMID 25403427, 2014).